STAT2 (signal transducer and activator of transcription 2)
Diseases named in the same sentence as STAT2 in open-access papers (continued):
Sharing a sentence is not in itself a finding about the gene and the disease.
infection (continued). "Use of human STAT2 transgenic mice with clinically relevant ZIKV isolates should be further investigated, as they may represent the most relevant model of human infection thus far." (PMID 34835050, 2021). "Regarding ZIKV and animal models, WT mice do not display strong sensibility to infection, due to the absence of degradation of murine STAT2 and a subsequent clearance of the virus." (PMID 32753493, 2020). "Compared to infection with the parental virus, rFCV 2280-F9 p30 infection displayed attenuated activities in reducing the level of IFNAR1 and inhibiting the phosphorylation of STAT1 and STAT2, whereas rFCV F9-2280 p30 displayed enhanced activities." (PMID 33075108, 2020). "We found that phosphorylation of STAT1 and STAT2 in A549 cells pre-treated with IL-36γ was inhibited at each post-infection point in time, while no significant changes in Mx1, PKR, IAV-Ca07 NP, and M1 protein were observed." (PMID 33193319, 2020). "Immunoblot analysis indicated that steady-state levels of STAT1 and STAT2 were not affected by infection, while phosphorylation of STAT1 at Tyr701 and STAT2 at Tyr690 (p-STAT1 or p-STAT2) was greatly reduced in TBEV infection compared with VSV-infected cells." (PMID 32196427, 2020). "In contrast to these observations, Bowen and colleagues reported a lack of STAT2 degradation in live infection in human A549 cells or in human DCs." (PMID 31673117, 2019). "In contrast, neither the STAT1 in the mock infection group nor another transcription factor STAT2 exhibited such reduction." (PMID 31191546, 2019). "Since we have shown that infection of Huh7.5 cells by ZIKV or DENV increased expression of PDLIM2 and both viruses are known to degrade STAT2, we examined whether PDLIM2 K/O cells were more resistant to ZIKV or DENV infections." (PMID 31374104, 2019). "However, at later times of infection (24–48 h) the expression of IRF3 returned back to basal levels and the expression of STAT2 was clearly enhanced." (PMID 31673117, 2019). "One reason for the resistance of WT mice to peripheral infection is that ZIKV fails to antagonize mouse Stat2, a key intermediate in the IFN signaling pathway, whereas it can promote degradation of human STAT2." (PMID 30384472, 2018). "We first observed a significant upregulation of STAT2 after three days of infection in microglia cells; however, this upregulation was absent in placenta cells." (PMID 30453684, 2018). "Together, these data show that in the absence of STAT2 signaling, both the M1 and M2 macrophage phenotypes are enhanced during super-infection." (PMID 30337919, 2018). "In this study, we demonstrate that STAT2 is significantly upregulated in infected microglia cells when compared with uninfected cells, but its levels do not change during the infection of placenta cells." (PMID 30453684, 2018). "STAT1, STAT2, and/or STAT3 tyrosine phosphorylation has been demonstrated by others to occur in fibroblast cells or macrophages at various times following infection with TC-MCMV." (PMID 28182772, 2017). "NS5 from both DENV and ZIKV degrades STAT2 in human or non-human primate cells but not in mice which likely contributes to resistance of immunocompetent mice to infection with these viruses." (PMID 28650973, 2017). "In the IFN-γ-untreated cells, parasite release into the culture medium became apparent ≈48 h post infection; and over the following three days extracellular parasite numbers increased about 10-fold, irrespective of STAT2 expression." (PMID 27780205, 2016). "The activity of C6 in blocking this pathway was likely to be masked to some degree during infection by the presence of the virus phosphatase VH1, which dephosphorylates STAT1 and STAT2 and is delivered into cells by the invading virion immediately after infection." (PMID 27907166, 2016).
infection (continued). "HCV did not apparently affect the phosphorylation of STAT1 and STAT2 at 24 hours post-infection, but it slightly increased the STAT1 phosphorylation at 48 hours post-infection, in agreement with its modest effect on ISRE." (PMID 26023919, 2015). "When cells expressing control non-targeting shRNA were infected with DENV2, STAT2 levels decreased by 4 hours post-infection." (PMID 23555265, 2013). "During infection, cleaved NS5 may direct STAT2 to an E3 ligase that targets it to the proteasome for degradation." (PMID 22590678, 2012). "WT or F170S HPIV1 infection also did not result in Stat2 degradation, in contrast to what is seen in HPIV2-infected cells." (PMID 22355301, 2012). "In summary, our findings indicate that HPIV1 infection did not lead to Stat1/2 degradation and that phosphorylation of Stat1 and Stat2 was reduced in WT HPIV1- and F170S HPIV1-infected cells following stimulation with IFN-α and IFN-β." (PMID 22355301, 2012). "A quantitative experimental setup reveals a time-dependent decline of endogenous STAT2 amounts upon infection with wt-MCMV but not upon infection with ΔM27-MCMV until 24 h post infection." (PMID 21698215, 2011). "Nevertheless, at late times of replication (≥48 h post infection) some STAT2 reduction was observed in ΔM27-MCMV infected cells, raising the possibility that additional MCMV gene products might affect STAT2." (PMID 21698215, 2011). "For example, infection of RSV, a close family member to hMPV, increases baseline ISRE promoter activity, but simultaneously suppresses IFN-β responsiveness of the ISRE by degrading STAT2." (PMID 21949722, 2011). "However, when LGTV infection occurred prior to IFN addition, phosphorylation of STAT1, STAT2, Tyk2, and Jak1 were all inhibited, suggesting that LGTV must establish a productive infection to counteract the IFN response." (PMID 21994750, 2011). "In the studies presented here, basal expression of STAT2 was unaffected in BMMs infected with DENV, but the level of infection of our BMMs may be as low as 1% (unpublished observation), suggesting NS5 has little direct effect upon STAT2 in our culture system." (PMID 21379341, 2011). "In the first 72 hours of infection, the single-deficient mice lacking STAT1 or STAT2 possessed 50–100 fold higher levels of viral RNA than wild type mice in the serum, spleen, and other visceral tissues, but remained resistant to DENV-induced death." (PMID 21379341, 2011). "In addition, it appeared that the phosphorylated forms of both STAT1 and STAT2 were stabilized in MPRV-infected cells, as they were still detectable after 24 h infection." (PMID 17325370, 2007). "Although STAT2 nuclear translocation increased during infection, the level was not significant." (PMID 41115066, 2025). "This IFN antagonism is species-specific; STAT2 from Homo sapiens is susceptible to NS5 antagonism, whereas Mus musculus STAT2 is resistant to NS5 antagonism, leading to differing infection outcomes with early viral clearance and no pathogenesis seen in immunocompetent mice." (PMID 38926343, 2024). "Although all viruses were able to significantly reduce the levels of STAT2 and RNA polymerase II at ISG promoters, species B viruses were particularly efficient at this as we did not detect significant levels of STAT2 or RNA polymerase II at ISG promoters after infection." (PMID 38940561, 2024). "Notably, our infection assay demonstrated that PK-15 Ifnar1 k/o and PK-15 Stat2 k/o cells supported the replication of both IAV and AKAV in the presence of poly (I:C), suggesting that the effect of Ifnar1 k/o is shared by Stat2 k/o." (PMID 37939052, 2023). "In addition, infection with WT Salmonella resulted in robust phosphorylation of ERK and STAT2." (PMID 37325511, 2023). "Thus, STAT2, N-myc interactor NMI and the RIG-I receptor were 1.6–1.8-fold induced upon infection." (PMID 34777295, 2021).
infection (continued). "Likewise, phosphorylation of STAT1 and STAT2 in 16HBE cells pre-treated with IL-36γ was mildly inhibited at 12 h after IAV-Ca07 infection, while no significant changes in Mx1, PKR, IAV-Ca07 NP, and M1 protein were observed." (PMID 33193319, 2020). "Together, from STAT1 and STAT2 germ-line mutation studies, it can be concluded that well-balanced and strictly controlled IFN-I and/or IFN-II-mediated immune responses are necessary but not sufficient to fight with infection." (PMID 29892288, 2018). "It is also in agreement with later studies describing the phenomenon of mice with a homozygous mutation Y701F STAT1, which were more susceptible to infection than STAT1-null mice and were not able to develop a similar type of STAT2/IRF9-mediated response to IFN as seen in STAT1-null mice." (PMID 29892288, 2018). "Our results indicate that STAT2 KO hamsters develop a disease course that shares features of disease observed in human cases and in other animal models of RVFV aerosol exposure, supporting the use of this BSL-2 infection model for countermeasure development efforts." (PMID 30463176, 2018). "Noticeably, STAT1/STAT2 and IRF9 form a transcriptional complex upon activation of type 1 IFN receptors; this complex can subsequently translocate to the nucleus and induce the expression of a broad spectrum of IFN-stimulated genes that serve to contain infection." (PMID 29084769, 2017). "Total expression of STAT2 did not change significantly with infection in either genotype." (PMID 27178303, 2016). "However, future studies will examine the cytokine expression profile over the course of infection in CD46+ pups, which may provide an explanation as to the reduction in STAT1 and STAT2 signaling by 10 dpi." (PMID 27178303, 2016). "STAT2 null mice also failed to clear a primed Cl13 infection." (PMID 25569216, 2015). "Notably, the adaptive immune response to adenovirus is not adversely affected in STAT2 knockout hamsters, and surviving hamsters cleared the infection by 7 to 10 days post challenge." (PMID 26291525, 2015). "Similarly, expression of several genes in the canonical IFN signaling pathway, including Ifng, Jak2, Stat1, Stat2, Socs1, Irf1, Irf9, Tap1, Ifitm1, Psmb8, Ifi35, Gas1 and Fit3 were up-regulated during infection by the mutant strain." (PMID 25201772, 2014). "While DENV NS5 alone is capable of binding STAT2, its ability to target STAT2 for degradation requires the presence of a protease cleavage signal upstream of the N terminus of NS5; thus mirroring the NS5 processing that occurs in the context of the DENV polyprotein during a natural infection." (PMID 21994652, 2010). "However, the extent of the control that this innate immune response exerts on the acute infection viremia is unclear: ZIKV has been demonstrated to be able to evade the effect of IFN signaling both by degrading STAT2 directly and by interfering with STAT2 and STAT3 phosphorylation." (PMID 33471814, 2021). "Interestingly, while IRF9, STAT1, and STAT2 were found in the nucleus of IFN-I treated PAM cells after 8 hpi, their localization was primarily cytoplasmic after 16 hpi, suggesting that both attenuated and virulent strains impair the nuclear translocation at late times of the infection." (PMID 34512601, 2021). "As we did not observe any differences between numbers of neutrophils transmigrating into the infection site between wild-type and Stat2-/- mice but there was a difference in MPO levels in the colon contents of these mice, we next determined whether Stat2-/- neutrophils were functional." (PMID 31009517, 2019). "However, Stat6 expression is not altered in the absence of STAT2 in super-infection." (PMID 30337919, 2018). "Thus, the enhanced vulnerability of type I IFN receptor deficient mice that almost uniformly develop symptomatic and often fatal infection, suggests STAT2-indepenent, type I IFN-dependent cell activation pathways may also be important in protection against ZIKV symptomatic infection." (PMID 29145516, 2017).
infection (continued). "Additionally, a recent report links STAT2 antagonism by ZIKV as a primary mechanism that the virus employs to down-regulate the Jak-STAT-controlled antiviral IFN-α/β response, underscoring the interplay between the Jak-STAT pathway and the establishment of a productive ZIKV infection." (PMID 28776046, 2017). "Western blot analysis showed IBV infection did not promote the phosphorylation of STAT1 and STAT2 and significantly inhibited IFN-β-induced STAT1 phosphorylation at the late stage of infection (18 h.p.i.)." (PMID 39602452, 2024). "STAT2 expression displayed no obvious changes during YN144 infection (YN144 vs Control, p-value > 0.05), but was notably decreased during YN15 infection (YN15 vs Control, p-value = 6.81E−08)." (PMID 33479333, 2021). "Previously we showed that EV-A71 infection did not alter the expression of IFNAR1 or JAK1, neither did it induce the degradation of STAT1 or STAT2." (PMID 34992585, 2021). "Others found no inhibition of STAT2 by HMPV; however, these experiments used a relatively low multiplicity of infection (MOI) in cell culture." (PMID 32635475, 2020). "FCV 2280 infection did not reduce the expression of total STAT1 and STAT2, but it significantly inhibited the levels of the phosphorylated STAT1 and STAT2 proteins in FCV-infected CRFK cells." (PMID 33075108, 2020). "During infection, non-structural protein 5 (NS5) protein inhibits IFN signaling by binding to STAT2 protein and promoting its degradation." (PMID 30625992, 2019). "By contrast, murine STAT2 is not targeted by ZIKV and as a consequence, immunocompetent mice are largely resistant to infection." (PMID 31511023, 2019). "Since STAT1, STAT2 and likely PDLIM2 protein levels vary among cell types and during infection, we cannot rule out that PDLIM2 does not direct interferon independent degradation of STAT1 in other situations." (PMID 31374104, 2019). "In mouse infection, NS5 was not able to bind murine STAT2, allowing IFN-mediated clearance of the virus." (PMID 30625992, 2019). "In co-IP assays performed at 8 h after infection, PML was found to interact with STAT1, STAT2, HDAC1, and HDAC2 in UV-HCMV-infected cells but not in uninfected cells." (PMID 25812002, 2015). "Some of these molecules (IRF7, IRF9, STAT1, STAT2) are known ISGs and were upregulated in wild-type but not in IFNAR1−/−IL-28Rα−/− epithelia at 24 hours post infection." (PMID 24278020, 2013). "The infection of Colo-679 cells with delNS1 or delNS1-IL15 did not induce STAT1 and STAT2 phosphorylation or MxA expression indicating a lack of interferon signalling." (PMID 22563505, 2012). "As expected, infection with M27-HA-MCMV, but not ΔM27-MCMV, induced STAT2 degradation in cells treated with control siRNA." (PMID 21698215, 2011). "It is known that in conventional infection, DENV-2 evades innate immune activation and IFN responses by a number of mechanisms, including its non-structural protein NS3’s inhibition of STAT1 and STAT2 signaling (36, –, 38)." (PMID 39902963, 2025). "An additional reason for caution is that a delayed IFN treatment might be unable to control an already established infection, as ZIKV non-structural protein NS5 is known to inhibit IFN signaling through STAT2 degradation." (PMID 35784373, 2022). "Notably, IRF9 expression was not affected by infection with either virulent or attenuated ASFV strains, supporting the idea that the virus specifically induces STAT1 and STAT2 degradation to counteract IFN-I signaling." (PMID 34512601, 2021). "These animals support infection, because ZIKV can antagonize human STAT2 but not mouse Stat239." (PMID 33077712, 2020). "In contrast, the lack of STAT2 expression in astrocytes and subsequent suppression of canonical JAK-STAT signaling might explain their high infection rate in cerebellar lesions." (PMID 30939763, 2019).
infection (continued). "Infection with ZIKV PR-2015 in the absence of IFNβ treatment induced minimal STAT1 phosphorylation and low levels of STAT2 phosphorylation, despite notable up-regulation of STAT1 and STAT2 total proteins." (PMID 28152048, 2017). "IFNAR−/−/IFNGR−/− (AG129) mice do not survive infection, yet STAT1−/−/IFNGR−/− mice remain healthy, demonstrating that STAT2 alone provides sufficient signaling via the type I IFN pathway for a functional antiviral response, despite the absence of both STAT1 and type II IFN signaling." (PMID 21379341, 2011). "Whilst infection of monocytes with EBV for 20 hours led to the phosphorylation of Jak1, STAT1 but not Tyk2 nor STAT2, increased phosphorylation of these proteins could not be observed upon restimulation of infected cells with IFNα." (PMID 20689596, 2010). "Interestingly, here we found that phosphorylation of STAT2 could be induced by several viruses at early infection stage, including influenza A virus (IAV), and such initial activation of STAT2 was independent of type I IFNs and JAK kinases." (PMID 36148221, 2022). "STAT1 mRNA levels were increased in both HRV16 and HRV1B infection than mock (p = 0.036 and p = 0.014, respectively) whereas STAT2 mRNA levels were increased in HRV1B infection, not in HRV16, than mock (p = 0.040), whereas IRF9 mRNA levels were not increased in HRV16 and HRV1B infection." (PMID 34838080, 2021).